CD44 (CD44 molecule (IN blood group))
Diseases named in the same sentence as CD44 in open-access papers (continued):
Sharing a sentence is not in itself a finding about the gene and the disease.
osteosarcoma (continued). "This dataset confirmed the elevated expression of CD44 in other sarcoma subgroups (osteosarcoma, rhabdomyosarcoma, chondrosarcoma, leiomyosarcoma, synovial sarcoma, fibrosarcoma, and liposarcoma) compared to Ewing sarcoma cell lines." (PMID 37511533, 2023). "Recent data showed that CD44 increases the resistance of osteosarcoma cells to doxorubicin by upregulating P-glycoprotein expression." (PMID 37958796, 2023). "Altogether, our results suggest that CD44 contributes to doxorubicin chemoresistance in osteosarcoma cells by regulating MDR1 expression and function." (PMID 35955749, 2022). "Knocking-out of CD44 using CRISPR/Cas9 system in the drug-resistant osteosarcoma cell lines KHOSR2 and U-2OSR2 (both resistant to Doxorubicin) showed significant inhibition of migration, invasion, proliferation, and resistance to doxorubicin." (PMID 35785191, 2022). "The analysis of the expression pattern in 59 osteosarcomas showed that IGF1R expression is highly correlated with ABCG2 expression and with CD44 expression in osteosarcoma patients under 10 years old." (PMID 35785191, 2022). "We observed that Cd44-positive osteosarcoma cells expressed significantly higher levels of Bcl2 mRNA, compared to Cd44-negative osteosarcoma cells, consistent with the pro-survival function of CD44." (PMID 35955749, 2022). "In our experiment, the effect of CD44 knockdown on biological behaviour of osteosarcoma was directly observed." (PMID 35264209, 2022). "For example, ectopic expression of miR-34a represses the expression of CD44 in two osteosarcoma cell sublines (F5M2 with highly metastatic potential and F4 with a low metastatic potential), inhibiting their migration and invasive ability." (PMID 35785191, 2022). "In another study, CRISPR/Cas9 was also used to knocking-out CD44 in the human osteosarcoma cell lines MNNG/HOS and 143B, both highly metastatic." (PMID 35785191, 2022). "In this study, we found that CD44 was highly expressed in osteosarcoma cell lines compared to hFOB1.19 human osteoblasts." (PMID 35264209, 2022). "This prompted us to investigate the relative contribution of CD44-dependent pathways to chemoresistance in osteosarcoma cells." (PMID 35955749, 2022). "Osteosarcoma cells highly express the cluster of differentiation 44 (CD44), which is a receptor for hyaluronic acid (HA), and the HA-binding participates in various tumor activities, including tumor progression, metastasis, and drug resistance." (PMID 35694235, 2022). "These tumors are the sarcomas in which more studies on CD44 have been carried out although the role of CD44 as a prognostic marker in osteosarcoma patients is controversial." (PMID 35785191, 2022). "A study of drug-resistant osteosarcoma cells showed that targeting CD44 using CRISPR/Cas9 technology reduced ABCB1 expression and significantly increased doxorubicin sensitivity." (PMID 35715750, 2022). "Gene silencing and CRISPR/Cas9-mediated knockout have been used to elucidate the role of CD44 in osteosarcoma pathogenesis, particularly in relation to resistance to treatment and metastasis formation." (PMID 35785191, 2022). "Cd44+/+ and Cd44−/− primary osteosarcomas clearly segregated from one another based on their RNA expression profiles." (PMID 35955749, 2022).
osteosarcoma (continued). "In order to study the relevance of CD44 in mediating chemoresistance, we previously isolated osteosarcoma cells from mice that developed endogenous osteosarcoma, due to a mutation of the tumor suppressor gene Nf2." (PMID 35955749, 2022). "In summary, these studies suggest that the CD44-miR-199a-3p axis and GAPLINC regulation are relevant regulators in the development of metastasis, tumor recurrence, and drug resistance in osteosarcoma cells mediated by CD44." (PMID 35785191, 2022). "The data from the characterization of osteosarcomas have revealed that CD44 (concretely CD44v6 isoform) is a potential and promising marker for prognosis and diagnosis." (PMID 35785191, 2022). "A total of 1592 genes were differentially expressed between Cd44-positive and Cd44-negative osteosarcomas." (PMID 35955749, 2022). "There are contradictory reports concerning the function of CD44 in osteosarcoma; however, most studies correlated CD44 expression with drug resistance, recurrence, higher potential of metastasis and poor survival." (PMID 35955749, 2022). "In this study, stem cell like cells were obtained from osteosarcoma cells by CD133+/CD44+ immunomagnetic beads double positive screening method and the isolated CD133+/CD44+ CSCs were identified by flow cytometry analysis." (PMID 29475441, 2018). "Transfection of miR-199a-3p significantly restored the sensitivity to chemotherapeutic drug doxorubicin in U-2OS cells suggesting that CD44 was a downstream target of miR-199a-3p in osteosarcoma." (PMID 29747682, 2018). "Several reports have indicated that CD44 expression contributes to aggressive progression in osteosarcoma as well as in hematologic malignancies." (PMID 30564299, 2018). "Knockdown of GAPLINC depressed osteosarcoma cell migration and invasion via inhibiting CD44 expression." (PMID 30177521, 2018). "Accordingly, shRNA-mediated CD44 knockdown significantly attenuated osteosarcoma cell migration, invasion, and viability especially in the metastatic subclones of U-2 OS and Saos-2 cells." (PMID 29371972, 2017). "We therefore examined the effect of EZH2 silencing on the protein expressions of cancer stem cell markers; include CD44 and Notch-3 in osteosarcoma cells." (PMID 27223261, 2016). "Overexpression of CD44 functions in promoting proliferation, metastasis, and drug resistance during osteosarcoma progression." (PMID 26079799, 2015). "The data showed poor response osteosarcoma patients demonstrated a significantly higher level of CD44 expression, in comparison with good response counterparts (P value of good response vs. poor response = 0.0484)." (PMID 26079799, 2015). "Our results also underscore the pivotal role of the CD44/miR-199a-3p interaction in determining malignancy in osteosarcoma." (PMID 26079799, 2015). "Different levels of CD44 expression were once again observed in these osteosarcoma patient samples, indicating endogenous expression of CD44 in tumor cells." (PMID 26079799, 2015). "Subsequently, we performed immunohistochemistry to evaluate the significance of CD44 in a large number of osteosarcoma patients." (PMID 26079799, 2015). "To investigate the clinical relevance between CD44 expression and osteosarcoma, we analyzed the relation of CD44 expression with osteosarcoma progression and prognosis." (PMID 26079799, 2015). "Taken together, these results suggest that the CD44-miR-199a-3p axis plays an important role in the development of metastasis, recurrence, and drug resistance of osteosarcoma." (PMID 26079799, 2015). "Our results showed that poor response osteosarcoma patients with less necrotic tumor demonstrated a significantly higher level of CD44 expression, in comparison with good response patients with a high percentage of necrotic tumors." (PMID 26079799, 2015).
osteosarcoma (continued). "Osteosarcoma cancer stem cell markers staining shown that the majority of CD44+ cells expressed CD47 albeit with different percentages (ranging from 80% to 99%)." (PMID 26093091, 2015). "Consistent with the tissue western blot result, osteosarcoma specimens presented various degrees of CD44 expression staining on the cell membrane." (PMID 26079799, 2015). "Transfection of miR-199a-3p significantly increased the drug sensitivity through down-regulation of CD44 in osteosarcoma cells." (PMID 26079799, 2015). "Aberrantly expressed miR-199a-3p in osteosarcoma leads to the degradation of CD44 mRNA and further generates decreased translation of CD44 protein." (PMID 26079799, 2015). "Our current study indicated that upregulation of CD44 is correlated with aggressive behaviors during osteosarcoma progression, including metastasis, recurrence, poor response to chemotherapy, as well as unfavorable prognosis." (PMID 26079799, 2015). "Herein, we investigated the role of cluster of differentiation 44 (CD44), a cell-surface glycoprotein involved in cell-cell interactions, cell adhesion, and migration in osteosarcoma." (PMID 26079799, 2015). "Results showed that CD44 was overexpressed in metastatic and recurrent osteosarcoma as compared with primary tumors." (PMID 26079799, 2015). "The expression levels of CD44 were significantly higher in metastatic tumors than in primary osteosarcoma tissues (P value of metastatic vs. primary <0.0001)." (PMID 26079799, 2015). "The TMA analysis revealed a significant correlation between stronger CD44 expression in surgical osteosarcoma specimens with shorter overall survival." (PMID 26079799, 2015). "The CD44-HA interaction has been found to enhance lung metastasis and chemoresistance in osteosarcoma cells." (PMID 26079799, 2015). "A positive impact of chemotherapy on patient survival has been seen in osteosarcoma with CD44 expression." (PMID 24491153, 2014). "For better analysis the relationship between CD44 expression and prognostic with the osteosarcoma, it is necessary to improve the experimental methods and detection methods, and to clear a unified quantitative standard." (PMID 25112408, 2014). "More well-designed clinical studies with large cases of osteosarcoma should be performed in the future to validate the relationship between CD44 expression level and prognosis of osteosarcoma patients." (PMID 25112408, 2014). "In this present study, we also discussed the relationship between overexpression of CD44 and clinicopathological parameters in osteosarcoma patients." (PMID 25112408, 2014). "In recent years, the expression of certain biological molecules has been identified as potential prognostic markers for osteosarcoma, including the expression of CD44." (PMID 25112408, 2014). "Future adequately multi-center designed prospective with larger sample size were of great value to confirm these findings and more clinical studies should be carried out before the application of CD44 in prognosis of osteosarcoma." (PMID 25112408, 2014). "The aim of this meta-analysis was carried out to investigate the relationship between CD44 expression and the survival in patients with osteosarcoma." (PMID 25112408, 2014). "With respect to osteosarcoma, the relationship between CD44 expression and prognosis was still controversial." (PMID 25112408, 2014). "To determine the behaviour of TECs in vitro, we selected two representative cell lines, TEC 1 and TEC 2 (from chondrosarcoma and osteosarcoma biopsies respectively and positive to CD44, CD105, CD90 and CD146), for further functional and molecular studies." (PMID 24216983, 2013). "CHA59, Saos-2, and HuO9 were immunoprobed for the expression of cell surface markers (CD133, CD24, CD166, CD326, CD44, ABCB1, ABCC1, ABCG2) previously reported to be associated with TSCs and/or osteosarcoma." (PMID 22870217, 2012).
osteosarcoma (continued). "Interestingly, CD44 was expressed at high levels in cell lines derived from osteosarcomas (CAL-72, SAOS-2, and U2OS), a chondrosarcoma (CAL-78), and a fibrosarcoma (HT1080) at mRNA and protein levels." (PMID 37511533, 2023). "Thus, in the case of osteosarcoma, CD44 and Nanog are outstanding markers when isolation is carried out with induction media, while markers such as ALDH and CXCR5 are found on biopsy samples." (PMID 37173919, 2023). "Overall, our results suggest that CD44 might be an important regulator of drug resistance and suggest that targeting CD44 can sensitize osteosarcoma to standard chemotherapy." (PMID 35955749, 2022). "Interestingly, the CD44 expression in osteosarcoma CSCs has been determined to be affected by pimozide treatment (a STAT5 inhibitor)." (PMID 35785191, 2022). "Besides, some innovative treatments such as HA-functionalized liposomes therapy have become an excellent CD44-mediated intracellular delivery system for osteosarcoma." (PMID 35785191, 2022). "Several of these innovative tools based on HA-functionalized liposomes have become an excellent CD44-mediated intracellular delivery system for doxorubicin (DOX) or photodynamic anticancer therapy in osteosarcomas: Chol-SS-mPEG/HA-L, HA-LsDOX, ALN–HA–SS–L–L/DOX, and HA-es-ZnPP." (PMID 35785191, 2022). "CD44 was proven as target of miR-199a-3p in osteosarcoma and in CSCC." (PMID 36499729, 2022). "Our studies suggest that targeting CD44-dependent pathways could serve as one option for sensitizing osteosarcoma to chemotherapy." (PMID 35955749, 2022). "MMP-9 is highly expressed in osteosarcoma, in our study, MMP-9 expression was down-regulated after CD44 was knocked down, reflecting the promoting effect of CD44 on invasion and metastasis of osteosarcoma cells, which is consistent with the role of CD44 in other tumours." (PMID 35264209, 2022). "The CD133+CD44+ cell population of osteosarcoma cells was reduced by circPIP5K1A knockdown." (PMID 34774083, 2021). "Since HA is the ligand of CD44, a highly expressed cancer stem cell marker on the osteosarcoma cell surface, the organic shell, HA-PEG polymer, could play a role in osteosarcoma targeting and sustained drug release." (PMID 33659241, 2021). "The knockdown of CD44 enhances the sensitivity of osteosarcoma cells to DOX." (PMID 34200614, 2021). "To identify the potential downstream target genes related to lincFOXF1 in osteosarcoma, we conducted qRT‐PCR to assess expression of multiple molecules (such as N‐cadherin, Integrin, CD44, ICAM‐1, Vimentin, Fibronectin, GIT1 and FOXF1) in osteosarcoma cells after gain or loss of lincFOXF1 function." (PMID 32945076, 2020). "Similarly, the K12 osteosarcoma cell line showed two populations with different CD44 expression levels (CD44high: 12500 and CD44mid: 1347), which bound HA with different MFI levels (HAmid 2144, HAhigh: 6941)." (PMID 30564299, 2018). "To study whether EL4 (murine T-cell lymphoma) and K12 (murine osteosarcoma) cell lines were able to respond to HA treatment, we first analyzed CD44 expression and HA binding ability in these tumor cell lines." (PMID 30564299, 2018). "Thus, we will further explore the regulatory mechanism between GAPLINC and CD44 in regulating osteosarcoma cell migration and invasion in a future study." (PMID 30177521, 2018). "Therefore, we supposed that GAPLINC regulates osteosarcoma cell migration and invasion through modulating CD44 expression." (PMID 30177521, 2018). "In addition, miR-34a was also found to inhibit the metastasis of osteosarcoma cells by repressing the expression of CD44, which indicates that miR-34a plays a tumor suppressor role." (PMID 27056900, 2016).
osteosarcoma (continued). "Furthermore, stem cell markers of CD44 and Notch-3 were decreased in osteosarcoma cells after inhibition of EZH2." (PMID 27223261, 2016). "We examined the relative protein levels of CD44 in osteoblast and osteosarcoma cell lines." (PMID 26079799, 2015). "We constructed a human osteosarcoma tissue microarray with 114 patient tumor specimens, including tumor tissues from primary, metastatic, and recurrent stages, and determined the expression of CD44 by immunohistochemistry." (PMID 26079799, 2015). "Recent studies have also shown that CD44 is a direct and functional target of miR-34a and enforced expression of miR-34a inhibits cancer stem cells, tumor regeneration and metastasis in prostate, osteosarcoma and renal carcinoma." (PMID 26036628, 2015). "However, few reports have studied the role of CD44 in a larger number of osteosarcoma patients with well-established clinical information." (PMID 26079799, 2015). "Based on the TMA results, we then explored the regulation mechanism of CD44 in osteosarcoma." (PMID 26079799, 2015). "Lung metastasis of osteosarcoma can be accelerated by upregulation of CD44 in vivo in mouse models." (PMID 26079799, 2015). "Although the molecular mechanisms elucidating osteosarcoma chemoresistance remains unknown, CD44 may play a pivotal part in chemoresistance on the basis of our analysis in clinical osteosarcoma tissues." (PMID 26079799, 2015). "miR-199a-3p may mediate the expression level of CD44 and thus impact the drug sensitivity of osteosarcoma cells." (PMID 26079799, 2015). "We demonstrated that CD44 is a direct target of miR-199a-3p in osteosarcoma." (PMID 26079799, 2015). "In the current study, we evaluated the role of CD44 in osteosarcoma progression and also identified that miR-199a-3p could modulate the drug sensitivity of osteosarcoma through targeting CD44." (PMID 26079799, 2015). "Moreover, we also showed that human osteosarcoma tissues across large sample numbers deriving from late stages (metastatic and recurrent stages) have higher CD44 protein expression than tumor samples in the primary stage." (PMID 26079799, 2015). "Moreover, miR-199a-3p inhibits the expression of CD44 in osteosarcoma both in a time and dose-dependent manner." (PMID 26079799, 2015). "Here, we found that CD44 is also a direct target of miR-199a-3p in osteosarcoma." (PMID 26079799, 2015). "Overexpression of miR-199a-3p significantly inhibited CD44 expression in osteosarcoma cells." (PMID 26079799, 2015). "Therefore, we strongly suggest conducting more prognostic studies for high CD44 expression in osteosarcoma." (PMID 25112408, 2014). "Finally, a total of six studies with 329 osteosarcoma patients were involved to estimate the relationship between CD44 expression and metastasis of tumor and overall survival." (PMID 25112408, 2014). "So in the future research, we will discuss the role of CD44 in chemoresistance of osteosarcoma." (PMID 25112408, 2014). "Therefore, the aim of this meta-analysis was carried out to investigate the relationship between CD44 expression and the survival in patients with osteosarcoma." (PMID 25112408, 2014). "We also discuss the possibility of using CD44 as a prognostic marker in osteosarcoma." (PMID 25112408, 2014). "Whether CD44 is a prognostic marker in osteosarcoma patients has been studied extensively, but the conclusions are inconsistent." (PMID 25112408, 2014). "Osteosarcoma presents as pleomorphic, malignant, spindle cells that secrete osteoid and express surface antigens commonly associated with mesenchymal stem cells (MSCs), such as CD29, CD44, CD56, CD90 and CD105." (PMID 24334332, 2013). "The levels of MDR1 protein could be reconstituted in Cd44-negative osteosarcoma cells by re-introduction of the smallest isoform of CD44- the so-called standard isoform (CD44s), suggesting that this isoform was sufficient to confer doxorubicin resistance in osteosarcoma cells." (PMID 35955749, 2022).